FRG1 (FSHD region gene 1)
Diseases named in the same sentence as FRG1 in open-access papers (continued):
Sharing a sentence is not in itself a finding about the gene and the disease.
breast carcinoma (continued). "The hazard ratio of FRG1 was 0.133 (95% CI 0.029–0.599, p = 0.009) for breast cancer patient’s death." (PMID 34795329, 2021). "In breast carcinoma, initially, we entered the top 20 FRG1 correlated genes (rs ≥ 0.353) to generate the multivariate cox regression model in the TCGA-BRCA (The Cancer Genome Atlas Breast Invasive Carcinoma) dataset." (PMID 34795329, 2021). "Another study supports our data indirectly, where FRG1 expression is reduced in migratory breast cancer cells." (PMID 28947680, 2017). "Overall, these data suggest that reduced FRG1 levels might be inducing breast cancer angiogenesis by the activation of the AKT/ERK signaling pathway in HUVECs." (PMID 36815234, 2023). "Therefore, our data strongly support the notion that FRG1 hinders EMT progression in breast cancer by inhibiting GM-CSF-mediated ERK activation." (PMID 36329016, 2022). "In the current study, we first report the FRG1-mediated regulation of GM-CSF in breast carcinoma." (PMID 36329016, 2022). "To check whether the effect of FRG1 was similar regardless of breast cancer molecular subtypes, we perturbed the expression of FRG1 in breast cancer cell lines of different origins and used the conditioned media to study its effect on human endothelial cell properties relevant to angiogenesis." (PMID 36815234, 2023). "However, the exact biological function of FRG1 in breast cancer and its mechanism are entirely unknown." (PMID 36329016, 2022). "Reduction in FRG1 expression enhanced EMT and increased cell proliferation, migration, and invasion, in breast cancer cell lines." (PMID 36329016, 2022). "We found an inverse expression pattern of FRG1 and phospho-ERK levels in breast cancer patient tissues, corroborating the in vitro and mouse model-based findings." (PMID 36329016, 2022). "To find out the correlation, we segregated breast cancer patient tissue samples according to their ER/PR/HER2 status and checked the expression of FRG1." (PMID 36329016, 2022). "Taken together, our findings imply an inverse relation between FRG1 and ERK activation in breast cancer patients." (PMID 36329016, 2022). "It was found in our study that RBM47, PCBP3, FRG1, SRP72 and other RBPs may regulate the AS of ITGA6, ADGRE5, TNC and other genes and affect the EMT process of breast cancer cells." (PMID 38783078, 2024). "RBM47, PCBP3, FRG1, SRP72 and other RBPs might regulate AS of ITGA6, ADGRE5, TNC and other genes and affect the EMT process of breast cancer cells." (PMID 38783078, 2024). "We generated stable cell lines with FRG1 level modulation in MCF7 (estrogen receptor positive cells; ER+) cells that harbors moderate expression of endogenous FRG1 and MDA‐MB‐231 (Triple negative breast cancer cells; TNBC) cells that has the basal level of endogenous FRG1." (PMID 36815234, 2023). "Moreover, FRG1 acts as a transcriptional repressor of GM‐CSF and suppresses the downstream ERK‐mediated EMT progression in breast cancer." (PMID 36815234, 2023). "We did not see any significant difference in FRG1 expression levels between ER + breast cancer tissues and TNBC patients (median FRG1 AS: 6 versus 5)." (PMID 36329016, 2022). "Which is supported by prior study, where reduced expression of FRG1 was observed in breast cancer cells with higher migratory levels, compared to average non-migratory breast cancer cells." (PMID 30975102, 2019). "By establishing the correlation network of differential RBPs and differential AS events, we found that RBM47, PCBP3, FRG1, SRP72, RBMS3 and other RBPs may regulate the AS of ITGA6, ADGRE5, TNC, COL6A3 and other cell adhesion genes, which may affect the EMT process of breast cancer cells." (PMID 38783078, 2024). "It emphasizes that the role of FRG1 in breast cancer is not subtype-specific." (PMID 36329016, 2022).
colon cancer (2 papers, 2017 to 2021). "Our previous research showed reduction in FRG1 protein expression in gastric cancer, colon cancer, and oral cavity cancer tissues by IHC analysis." (PMID 34795329, 2021). "In colon cancer, distribution pattern showed that ~80% cases had strong FRG1 staining in uninvolved tissue, compared with ~40% cases with strong FRG1 staining in tumor tissue." (PMID 28947680, 2017). "Surgically resected tumor tissue with uninvolved region of oral cancer, gastric cancer, and colon cancer were stained with FRG1 antibody." (PMID 28947680, 2017). "Similarly, in gastric and colon cancers, FRG1 levels in tumor were reduced in 66.66% (6/9) and 63.63% (7/11) compared with the uninvolved control, respectively." (PMID 28947680, 2017).
Facioscapulohumeral dystrophy (2 papers, 2008 to 2012). Facioscapulohumeral muscular dystrophy (FSHD) is characterized by progressive muscle weakness with focal involvement of the facial, shoulder and limb muscles. "We thus validate our miRNome results in single muscle fibres isolated from other animal models of MDs such as the alpha-Sgca-null and the FRG1 over-expressing mice, respectively animal models of a limb-girdle 2D (LMGD-2D) and of Facioscapulohumeral dystrophy (FSHD)." (PMID 22912879, 2012).
fibrous tumor of (2 papers, 2021 to 2022). "Whole-exome sequencing identified some deleterious mutations in the FRG1 gene in calcifying fibrous tumor of the pleura." (PMID 36329016, 2022). "Many studies have demonstrated its involvement in tumorigenesis and tumor progression: FRG1 mutations occur in patients with thyroid cancer and calcifying fibrous tumor of pleura." (PMID 34117242, 2021).
follicular thyroid cancer (2 papers, 2019 to 2021). "Deleterious mutations of FRG1, which had been identified in calcified pleura fibrous tumor and follicular thyroid cancer, were suggested to contribute to tumorigenesis." (PMID 34386035, 2021). "In addition, four KIT-mutant samples contained somatic single nucleotide variants in FRG1 (q < 0.01), a cancer driver gene in follicular thyroid cancer." (PMID 30867899, 2019).
gastric cancer (2 papers, 2017 to 2021). A primary or metastatic malignant neoplasm involving the stomach. "Survival analysis revealed that low FRG1 expression was associated with poor prognosis in OS of patients, in lung cancer (HR =0.84, P-value =0.0058) and in gastric cancer (HR =0.56, P-value =1.8 × 10−8)." (PMID 28947680, 2017). "We observed that the patients with low FRG1 mRNA expression were more frequent in the cervix and gastric cancers." (PMID 34795329, 2021). "High FRG1 mRNA expression correlated with better survival in the cervix and gastric cancer patients." (PMID 34795329, 2021). "Distribution pattern of FRG1 staining in gastric cancer revealed that more than 40% cases had strong staining and 60% cases had moderate staining in uninvolved tissue, whereas in tumor total 40% cases belonged to strong to moderate group." (PMID 28947680, 2017). "In cervix and gastric cancers, we found a clear difference in the OS between the low and high FRG1 mRNA expression groups, but the difference was not prominent in breast, lung, and liver cancers." (PMID 34795329, 2021). "Out of these four cancer types, Oncomine data suggest that FRG1 expression was reduced in breast, lung, and ovarian cancer but in gastric cancer, not a single analysis was found to be significant." (PMID 28947680, 2017).
lung adenocarcinoma (2 papers, 2019 to 2021). A carcinoma that arises from the lung and is characterized by the presence of malignant glandular epithelial cells. "The age‐related association was identified as top‐rank with mutations occurring in two genes FRG1 and KMT2C FRG1 mutations were detected in 8 (40.0%) young and 3 (12.5%) older lung adenocarcinoma patients (P = 0.081)." (PMID 30821106, 2019). "Genetic alterations in FRG1 and KMT2C (MLL3) were both significantly associated with a younger age in patients diagnosed with lung adenocarcinoma, especially after correcting for potential predictors, for example, sex and smoking history." (PMID 30821106, 2019). "The top 20 FRG1 correlated genes (rs ≥ 0.535) and FRG1 were added in multivariate cox regression model using TCGA-MESO (The Cancer Genome Atlas Mesothelioma), TCGA-LUAD (The Cancer Genome Atlas Lung Adenocarcinoma) and TCGA-LUSC (The Cancer Genome Atlas Lung Squamous Cell Carcinoma) datasets." (PMID 34795329, 2021). "Although no age‐related differences were detected in the numbers of lung adenocarcinoma patients harboring well‐known gene variants, mutations in FRG1 and KMT2C were associated with a younger age especially after correcting for tobacco smoking and sex (FRG1: P = 0.027, KMT2C: P = 0.046)." (PMID 30821106, 2019).
lung carcinoma (2 papers, 2017 to 2021). "The final model had 17 genes where the hazard ratio of FRG1 was 0.235 (95% CI 0.074–0.742, p = 0.014) for lung cancer patient’s death." (PMID 34795329, 2021). "To investigate the prognostic effect of FRG1 on lung carcinoma patients, we applied the same strategy." (PMID 34795329, 2021).
prostate tumor (2 papers, 2019 to 2021). "FRG1 expression was reduced in prostate tumor tissues compared to normal tissue." (PMID 34795329, 2021).
cholangiocarcinoma (1 paper, 2021). A carcinoma that arises from the intrahepatic biliary tree (intrahepatic cholangiocarcinoma) or from the junction, or adjacent to the junction, of the right and left hepatic ducts (hilar cholangiocarcinoma). "The top 20 FRG1 correlated genes, with rs cutoff ≥ 0.539, were used to generate the multivariate cox regression model using TCGA-LIHC (The Cancer Genome Atlas Liver Hepatocellular Carcinoma) and TCGA-CHOL (The Cancer Genome Atlas Cholangiocarcinoma) datasets." (PMID 34795329, 2021).
colorectal cancer (1 paper, 2021). A primary or metastatic malignant neoplasm that affects the colon or rectum. "The hazard ratio of FRG1 was 0.478 (95% CI 0.081–2.824, p = 0.415) for colorectal cancer patient’s death." (PMID 34795329, 2021).
Duchenne muscular dystrophy (1 paper, 2013). Duchenne muscular dystrophy (DMD) is a neuromuscular disease characterized by rapidly progressive muscle weakness and wasting due to degeneration of skeletal, smooth and cardiac muscle. "We also found that the level of Rbfox1 down-regulation parallels the severity of the disease in different muscles of FRG1 mice, while it is expressed at normal levels in the mouse model of Duchenne muscular dystrophy." (PMID 23300487, 2013). "The fact that Capn3 E6- is already increased in pre-symptomatic FRG1 mice and that its expression is normal in the mouse model of Duchenne muscular dystrophy suggests that altered Capn3 splicing is a primary consequence of FRG1 overexpression and is not simply secondary to muscle wasting." (PMID 23300487, 2013).
limb-girdle muscular dystrophy type 2L (1 paper, 2020). "Defect or delay in the fusion stage was reported in FRG1 mouse model for FSHD primary myoblasts and limb-girdle muscular dystrophy type 2L (LGMD2L) Ano5−/− knockout mouse model." (PMID 32523512, 2020).
liver cancer (1 paper, 2021). An epithelial or non-epithelial malignant neoplasm that arises from the liver. "In breast, lung, and liver cancers, we found a distinct difference in the OS between the low and high FRG1 mRNA expression groups in the multigene model, suggesting an independent role of FRG1 in survival." (PMID 34795329, 2021). "As expected, we observed a clear effect of FRG1 expression in breast, lung, and liver cancers also after multivariate cox regression analysis." (PMID 34795329, 2021). "The final model had 16 genes where the hazard ratio of FRG1 was 0.18 (95% CI 0.034–0.948, p = 0.043) for liver cancer patient’s death." (PMID 34795329, 2021). "Therefore, we did multigene model-based analysis in breast, lung, colorectal, and liver cancers to get a clear idea about the effect of FRG1 mRNA expression on OS." (PMID 34795329, 2021).
lymph node metastasis (1 paper, 2023). "Other genes alternating in both primary tumors and lymph node metastasis tumors within individuals include CALR (Calreticulin), FRG1(FSHD Region Gene 1), and ACTG1 (Actin Gamma 1)." (PMID 36653483, 2023).
oral cancer (1 paper, 2017). "In oral cancer, we observed that FRG1 levels were reduced in 61.11% of tumor cases, i.e. in 11/18 cases, compared with uninvolved region." (PMID 28947680, 2017).
prostate adenocarcinoma (1 paper, 2019). "FRG1 expression is reduced in prostate adenocarcinoma tissue." (PMID 30975102, 2019).
tumor (12 papers, 2017 to 2025). "Expression analysis revealed that ectopic expression of FRG1 leads to reduction (3.3-fold, P-value =0.021) in G-CSF expression, which is the key molecule associated with cell migration and tumor progression." (PMID 28947680, 2017). "Further, to identify if this association is tumor angiogenesis dependent, we evaluated the effect of FRG1 expression in endothelial cells and epithelial cells." (PMID 28947680, 2017). "Further, immunohistochemistry was done to identify FRG1 expression levels in various cancers and its association with tumor angiogenesis." (PMID 28947680, 2017). "The present study was taken up to explore the association of FRG1 expression with tumor progression." (PMID 28947680, 2017). "FRG1 regulates various muscle-related functions, but studies have proposed its role in development and angiogenesis also, where it is involved with tumor-associated molecules." (PMID 28947680, 2017). "Since earlier studies suggest association of FRG1 with vascular abnormalities and our in vitro data show that higher levels of FRG1 lead to reduction in tubule formation, therefore, we checked whether FRG1 level is associated with tumor angiogenesis." (PMID 28947680, 2017). "In spite of having a role as metastatic suppressor, involvement of FRG1 in tumor angiogenesis was mostly overlooked." (PMID 36815234, 2023). "This study was taken up to explore the exact role of FRG1 in tumor angiogenesis, and its mechanistic attribute to ascertain if it is upstream of VEGF A or FGF2." (PMID 36815234, 2023). "Overall, these results show pro‐angiogenic potential of tumor cells with reduced expression of FRG1." (PMID 36815234, 2023). "To get insights into the molecular mechanism behind FRG1‐mediated tumor angiogenesis, we first examined the effect of FRG1 perturbation on VEGF A by ELISA." (PMID 36815234, 2023). "To demonstrate the effect of FRG1 expression on tumor angiogenesis in vivo, we validated our in vitro findings in multiple animal models." (PMID 36815234, 2023). "The therapeutic potential of anti-GM-CSF therapy was evident by reduced tumor size, when tumors with decreased FRG1 were treated with anti-GM-CSF mAb." (PMID 36329016, 2022). "Further, FRG1 knockdown can lead to significantly enhanced invasion and migration abilities of tumor cells." (PMID 34117242, 2021). "Staining pattern of FRG1 was mostly moderate to weak in both tumor and uninvolved tissue, with 22% weak in tumor to 40% weak expression in uninvolved tissue." (PMID 30975102, 2019). "FRG1 knockdown led to activation of p38 MAPK; activation of p38 MAPK has been associated with tumor progression previously." (PMID 30975102, 2019). "Further, to understand the effect of FRG1 expression on tumor angiogenesis, correlation analysis was done for FRG1 IRS and MVD." (PMID 30975102, 2019). "Immunoreactive score (IRS), quantified for the staining pattern, revealed that 52 out of 100 cases (p value < 0.0005) had reduced FRG1 expression in tumor tissue." (PMID 30975102, 2019). "The staining pattern revealed significant reduction of FRG1 expression levels in tumor cells, compared to uninvolved secretory ductal epithelial cells of prostate." (PMID 30975102, 2019). "Significant reduction in FRG1 expression levels was observed in tumor, when compared with levels in uninvolved tissue." (PMID 28947680, 2017). "Comparison of Allred score for FRG1 in tumor and uninvolved tissue, showed significant (P-value =0.0001) reduction in FRG1 levels in tumor (median value =3) to uninvolved (median value =6)." (PMID 28947680, 2017). "Since G-CSF and MMP10, which are known to promote tumor growth, levels were affected by FRG1, we looked for FRG1 expression in tumor tissues." (PMID 28947680, 2017). "To further validate the in silico data and to derive correlation between FRG1 expression and tumorigenesis from cell-based studies, we checked FRG1 expression levels in tumor tissues." (PMID 28947680, 2017).
tumor (continued). "Reduced angiogenesis during FRG1 overexpression clearly points toward tumor suppressive role of FRG1." (PMID 28947680, 2017). "Treatment of dental epithelial cell line, mDEC6 with bone morphogenetic protein 4 (BMP4), a known tumor inhibitor, leads to translocation of FRG1 from the nucleus to the cytoplasm." (PMID 28947680, 2017). "was the first direct indication of the possible role of FRG1 in human tumor angiogenesis." (PMID 36815234, 2023). "Correspondingly, ectopic expression of FRG1 significantly reduced tumor volume and weight." (PMID 36329016, 2022). "FRG1 knockdown significantly increased tumor volume and weight." (PMID 36329016, 2022). "FRG1 depletion in the mouse model increased tumor volume, phospho-ERK, and EMT marker levels." (PMID 36329016, 2022). "Functionally, FRG1 may act as tumor suppress gene since its expression is reduced in various types of tumor, such as prostate, breast, lung, gastric, etc38,39." (PMID 34117242, 2021). "6% uninvolved tissue had high FRG1 staining compared to 2% of tumor tissue." (PMID 30975102, 2019). "Expression of FRG1 was higher in uninvolved epithelial tissues, compared with the tumor." (PMID 28947680, 2017). "Our first study is to identify reduced expression of FRG1 in tumor tissues." (PMID 28947680, 2017). "Nevertheless, an important question still remains to be answered, i.e. whether FRG1 expression affects cell proliferation during tumor progression." (PMID 28947680, 2017). "Overall, these data indicate a possible role of FRG1 in tumor progression." (PMID 28947680, 2017). "Reduced expression of FRG1 in patient tumor tissues also supports tumor suppressive role of FRG1." (PMID 28947680, 2017). "Thus, a well stratified and higher sample size could provide a more conclusive picture regarding localization and role of FRG1 in tumor angiogenesis." (PMID 30975102, 2019). "Our data suggest that FRG1 may have tumor suppressor activity as its overexpression inhibits cellular migration and invasion and vice versa, and both these properties are important for the metastatic growth of tumor." (PMID 28947680, 2017). "Hence in vitro data provide us with the first-hand information regarding involvement of FRG1 in angiogenesis in humans; but question still remains for the tumor patients which provides parallel insights into the findings in FSHD patients with vasculature abnormalities." (PMID 28947680, 2017). "FRG1 may affect tumor progression by affecting tumor cell migration and invasion." (PMID 28947680, 2017). "Therefore, FRG1 expression levels might be crucial for tumor progression through tumor angiogenesis or independently." (PMID 28947680, 2017). "Further, we could not observe association between FRG1 levels in tumor and tumor MVD." (PMID 28947680, 2017). "Overall, patient IHC data revealed that FRG1 expression is reduced in tumor tissue but does not correlate with MVD count." (PMID 30975102, 2019). "Until now, there is no direct evidence showing the role of FRG1 in tumor angiogenesis and tumor progression." (PMID 28947680, 2017). "FRG1 staining was negative in 39% of tumor tissue compared to 14% of uninvolved tissue." (PMID 30975102, 2019). "Generally, correlation analysis suggests that FRG1 expression levels may not have a role in tumor angiogenesis." (PMID 28947680, 2017). "Moreover, we also found some genes that have not been identified as tumour-associated genes by Cancer Gene Census also encode potential neoantigens, such as MUC4, FAM194B, OPRD1 and FRG1." (PMID 28484631, 2017). "FRG1 expression (IRS) showed significant negative correlation (Spearman correlation, 2-tailed, r2 -0.285, p value < 0.005) with tumor grade (Gleason score)." (PMID 30975102, 2019).